CAV1 (caveolin 1)
Diseases named in the same sentence as CAV1 in open-access papers (continued):
Sharing a sentence is not in itself a finding about the gene and the disease.
metabolic syndrome (continued). "Another example is the caveolin-1 gene (CAV1) variant associated with IR which is also associated with metabolic syndrome, especially in non-obese subjects." (PMID 31331009, 2019). "We concluded that CAV-1 plays a critical role in inhibiting CypA-mediated ROS production, improving dyslipidemia, maintaining mitochondrial function, and suppressing oxidative stress responses that are vital for cell survival in hypercholesterol-affected renal organs." (PMID 27124120, 2016). "In this paper, we conclude that CAV-1 plays a crucial role in inhibiting CypA-mediated ROS production, improving dyslipidemia, maintaining mitochondrial function, and attenuating oxidative stress responses that are vital for cell survival in hypercholesterol-affected renal organs." (PMID 27124120, 2016). "Dyslipidemia evidenced in Cav-1-/- and CD36-/- mice is congruent once more with our hypothesis on involvement of Caveolin genes in the control of cholesterol homeostasis." (PMID 19134193, 2009). "CAV-1 and CAVIN-1 mRNA are highly expressed in visceral and subcutaneous adipose tissues, particularly among obese individuals, which may be associated with dyslipidemia, and atherosclerosis." (PMID 38268038, 2024). "Here, we analyzed the role of caveolin-1 (Cav-1) in determining the stiffness of endothelial cells (EC) exposed to oxidized low density lipoprotein (oxLDL) under static and hemodynamic conditions in vitro and of aortic endothelium in vivo in mouse models of dyslipidemia and ageing." (PMID 36280774, 2022). "Similarly, statins are often used to treat dyslipidemias associated with HIV disease and this may also promote Cav-1 up-regulation by enhanced SREBP interaction with the Cav-1 promoter." (PMID 28587148, 2017). "In the present study, we tested the hypothesis that CAV-1 improves dyslipidemia, inhibits cyclophilin A (CypA)- mediated ROS production, prevents mitochondrial compensatory action and attenuates oxidative stress responses in cholesterol-induced hypercholesterolemia." (PMID 27124120, 2016). "Moreover, Cav-1 is involved in SMC differentiation and dyslipidemia confirming the importance of lipid homeostasis in the atherosclerotic phenotype." (PMID 19134193, 2009).
Cerebral ischemia (37 papers, 2010 to 2025). Restriction of arterial blood supply to the brain associated with insufficient oxygenation to support the metabolic requirements of the tissue. "In a cerebral ischemia injury model, Caveolin-1 deficiency also mediated BBB leakage." (PMID 30670717, 2019). "In addition, Cav-1 KO mice show higher rates of apoptotic cell death and larger infarct volumes than wild- in ischemic brains, and the production of NO induces the loss of Cav-1 in focal cerebral ischemia and reperfusion injury." (PMID 25741233, 2015). "After cerebral ischemia, miR-199a-5p regulates Cav-1 expression, leading to increased expression of BDNF and VEGF, promoting neural stem cell differentiation and endogenous neurogenesis." (PMID 38922036, 2024). "Recent studies have revealed that storax-induced attenuation of BBB impairment, which helps to halt the progression of cerebral ischemia, occurs through the upregulation of Mfsd2a and concurrent inhibition of Cav-1 in the endothelial cells." (PMID 39273347, 2024). "MiR-199a-5p promotes functional recovery after cerebral ischemia by inhibiting Cav-1 to facilitate neurogenesis; it has been shown to be downregulated in rats with cerebral ischemia." (PMID 39407977, 2024). "Results of the present study supported a critical role of miR‐199a‐5p by inhibiting Cav‐1 expression to promote the neuronal differentiation of NSCs and endogenous neurogenesis in rats after cerebral ischemia." (PMID 37349971, 2023). "Recent research confirmed that storax attenuated BBB disruption by upregulating Mfsd2a and inhibiting Cav-1 in the endothelial cells in order to arrest the progression of cerebral ischemia." (PMID 37762391, 2023). "Most importantly, the expression of caveolin-1 (cav-1) was decreased in rats that underwent cerebral ischemia and reperfusion, which was reserved by treatment with L-NAME." (PMID 35457061, 2022). "In our research, we confirmed that storax attenuated BBB disruption by upregulating Mfsd2a and inhibiting Cav-1 in the ECs, to arrest the progression of cerebral ischemia." (PMID 35873558, 2022). "More recent research showed that loss of Cav-1 results in decreased AQP4 expression and impaired perivascular AQP4 covering after cerebral ischemia associated with altered reactive astrocyte morphology and enhanced brain swelling." (PMID 35873558, 2022). "The protein expression of caveolin-1 was diminished after cerebral ischemia–reperfusion injury, while both eNOS and iNOS protein expression was elevated." (PMID 34829948, 2021). "In summary, we show for the first time that loss of Cav-1 results in decreased AQP4 expression and impaired perivascular AQP4 covering after cerebral ischemia associated with altered reactive astrocyte morphology and enhanced brain swelling." (PMID 32523952, 2020). "Choi and colleagues showed that Cav-1 overexpression attenuated brain edema after cerebral ischemia in the rat." (PMID 32523952, 2020). "Further study is needed to determine the mechanisms by which Cav-1 promotes neuroplasticity following cerebral ischemia through the NF-κB pathway." (PMID 31673241, 2019). "Caveolin-1 expression was higher at 7 d after cerebral ischemia than at 14 d in all the model groups (P < 0.05)." (PMID 30622670, 2018). "The mRNA expression of Caveolin-1 decreased in rats after cerebral ischemia, and there was significant difference from the sham group (P < 0.05)." (PMID 30622670, 2018). "Experimental models of cerebral ischemia indicate that the downregulation of cav-1 membrane protein results in increased BBB permeability." (PMID 30572925, 2018). "Compared with the sham group, Caveolin-1 protein expression significantly increased after cerebral ischemia in rats (P < 0.01)." (PMID 30622670, 2018). "What is more, Cav-1 has been reported to play an important role in regulating BBB permeability in experimental cerebral ischemia/reperfusion injury." (PMID 27725888, 2016).
Cerebral ischemia (continued). "Meanwhile, with focal cerebral ischemia-reperfusion, cav-1 KO mice displayed higher MMPs activities and BBB permeability than WT mice." (PMID 23565108, 2013). "Next, they investigated the effects of cerebral ischemia in Cav-1 and Cav-2 KO mice and have shown marked increase of cerebral volume of infarction and elevated apoptotic index in Cav-1 KO relative to WT and Cav-2 KO mice." (PMID 26605130, 2012). "All our results suggested that BMSC-sEVs could regulate Cav-1-mediated autophagic degradation of ZO-1 and Occludin after cerebral ischemia." (PMID 39781452, 2025). "MiR‐199a‐5p may target and inhibit Cav‐1 to enhance neurogenesis and thus promote functional recovery after cerebral ischemia." (PMID 37349971, 2023). "Caveolin-1 was also deemed essential in post-injury remodeling of the neuronal membrane following different insults, such as brain injury by cerebral ischemia." (PMID 37228704, 2023). "Caveolin-1 has been found to be reduced after cerebral ischemia–reperfusion injury." (PMID 34829948, 2021). "Here we tested whether Cav-1 regulates AQP4 expression in the perivascular region after brain ischemia in mice." (PMID 32523952, 2020). "Targeting Cav-1 may be a promising therapeutic strategy to enhance neuroplasticity after cerebral ischemia." (PMID 31673241, 2019). "Recently, it has been shown that cav-1 has a beneficial role in cerebral ischemia." (PMID 30572925, 2018). "Contrary to the view that cav-1 is neuroprotective in cerebral ischemia, there are a host of studies demonstrating that cav-1 may damage the BBB." (PMID 30572925, 2018). "However, some natural active compounds, such as green tea polyphenols, show a protective role in brain ischemia which is correlated with a decrease in cav-1." (PMID 30572925, 2018). "Thus, we logically address that cav-1 inhibits inflammation via maintaining the integrity of BBB under brain ischemia condition." (PMID 30572925, 2018). "However, some researchers believe that the protective effects in brain ischemia of several natural active compounds are related to the reduced expression of cav-1." (PMID 30572925, 2018). "In the mouse, cerebral ischemia may induce increases in endothelial caveolin-1 and -2 protein levels." (PMID 27297022, 2016). "In addition, the molecular mechanisms of maintaining BBB integrity in which Cav-1 plays an important role through inhibition of MMPs activity and protection of TJ protein during cerebral ischemia-reperfusion injury have been reported in our previous study." (PMID 27725888, 2016). "Hippocampi synaptosomes from Cav-1 KO mice showed reduced PSD-95, NR2A, NR2B, and Cav-1, an inability to be protected against cerebral ischemia-reperfusion injury compared to young WT mice, increased Aβ, P-Tau, and astrogliosis, decreased cerebrovascular volume compared to young WT mice." (PMID 21203469, 2010). "Our data suggest that not only are MLR and Cav-1 essential for maintaining and stabilizing proper synaptic signaling and neuroprotection against cerebral ischemia, but they also may serve to slow the amyloidogenic process of APP seen in AD brains." (PMID 21203469, 2010). "Here, we investigated if Cav-1 is involved in AQP4 expression and cellular distribution after brain ischemia relating to astrogliosis and brain swelling." (PMID 32523952, 2020). "The adverse influence on angiogenesis after Cav-1 knockout has been confirmed in multiple disease models, including hindlimb ischemia, scleroderma fibroblasts, colitis, AMI, and cerebral ischemia." (PMID 31178960, 2019). "Cav-1(−/−) mice demonstrated higher MMP activity and BBB permeability than cav-1 (+/+) mice in a focal cerebral ischemia-reperfusion model." (PMID 30572925, 2018). "Strategies for Cav-1 OE represent a novel therapeutic approach to reduce BBB disruption and subsequent brain edema during cerebral ischemia." (PMID 27708218, 2016).
Cerebral ischemia (continued). "Current evidence indicates that the interactions of RNS, cav-1, and MMPs are critical signal pathways in BBB disruption and infarction enlargement during cerebral ischemia-reperfusion injury." (PMID 23565108, 2013). "Furthermore, we injected the cholesterol-modified Cav-1 siRNA by ICV approach and examined the tight junction and autophagy proteins expression in ischemic mice brain microvessels after 24 h cerebral ischemia." (PMID 39781452, 2025). "Discussion: Cav-1 can affect CI injury by regulating MQC, and this mechanism may be another target of BHD for anti-cerebral ischemia injury." (PMID 37234709, 2023). "The lack of caveolin-1, in Cav-1−/− knockout mice resulted in decreased AQP4 expression and impaired perivascular AQP4 coverage after cerebral ischemia, which in turn is associated with increased brain swelling in this mouse type." (PMID 35454119, 2022). "In addition, knockout or knockdown of caveolin-1 increased blood–brain barrier (BBB) permeability and cell damage after cerebral ischemia-reperfusion by activating the NO/Cav-1/MMP signaling cascade." (PMID 36289917, 2022). "Absence of Cav-1 was associated with perivascular changes in AQP4 expression and enhanced brain swelling at 3 days after cerebral ischemia." (PMID 32523952, 2020). "To date, however, a direct role of Cav-1 in vasogenic cerebral edema due to BBB disruption following middle cerebral artery (MCA) occlusion (MCAO), the most common physiologic model of cerebral ischemia-reperfusion, in rats overexpressing the Cav-1 gene has yet to be demonstrated." (PMID 27708218, 2016).
endothelial dysfunction (36 papers, 2012 to 2026). In vascular diseases, endothelial dysfunction is a systemic pathological state of the endothelium (the inner lining of blood vessels) and can be broadly defined as an imbalance between vasodilating and vasoconstricting substances produced by (or acting on) the endothelium. "Cav-1 has been implicated in critical stages of atherosclerotic plaque development, including endothelial dysfunction, lipid accumulation, and inflammation." (PMID 40243482, 2025). "The eNOS G894T variant contributes to endothelial dysfunction by diminishing eNOS and caveolin-1 interaction, altering eNOS caveolar localization and reducing the shear-dependent eNOS activation." (PMID 36819141, 2023). "Direct binding of eNOS to the scaffolding domain of Cav-1 is a well-accepted mechanism to repress eNOS activity that is associated with endothelial dysfunction and cardiovascular disease." (PMID 33051481, 2020). "Another study using adult hypothyroidism and age-matched euthyroid rats not only confirmed the inductive effect of hypothyroidism on cav-1, but also observed decreased eNOS activities and further revealed a possible mechanism underlying the link between hypothyroid and endothelial dysfunction." (PMID 25452768, 2015). "The common pathological mechanisms underlying Cav-1-autophagy interactions include oxidative stress, inflammatory cascades, and metabolic reprogramming, leading to common pathological phenotypes such as endothelial dysfunction, fibrosis, and barrier disruption." (PMID 41030451, 2025). "Upregulation of cav-1 contributes to high-salt diet-induced endothelial dysfunction and hypertension through decreased eNOS activation." (PMID 38664801, 2024). "Previous studies have demonstrated that in the endothelium, NO is synthesized by eNOS and is negatively regulated by Cav-1; dysregulation of eNOS and CAV-1 contribute to endothelial dysfunction in diabetic dyslipidemia." (PMID 36879344, 2023). "MS resulted in cardiac dysfunction, remodeling by regulating caveolae and CAV-1 expression, and endothelial dysfunction." (PMID 36879344, 2023). "Chronic hypoxia and ischemia led to endothelial dysfunction and diminished Cav-1 expression, triggering HSP90α secretion from endothelial cells." (PMID 36357389, 2022). "Our study suggests that CAV-1-mediated endothelial dysfunction plays a critical role in the pathogenesis of HACE and provides a theoretical basis for the early prevention and treatment of HACE." (PMID 36253854, 2022). "Global Cav-1 knockout mice have endothelial dysfunction, and transgenic Cav-1 re-expression in the endothelium of Cav-1 knockout mice rescues the endothelial function." (PMID 34456860, 2021). "Male Apolipoprotein E knock-out (ApoE−/−) mice fed a high fat (HF) diet developed a significant endothelial dysfunction attested by atherosclerotic plaques and increasing abundance of caveolin-1 in aorta." (PMID 31578395, 2019). "Taken together with previous studies indicating a vasculoprotective role of cav-1 and caveolae, our in vitro and in vivo findings suggest that atheroprone flow can lead to endothelial dysfunction through decreased cav-1/caveolae expression and localization." (PMID 30563532, 2018). "Specifically, we propose that glycocalyx degradation can induce pro-atherosclerotic endothelial dysfunction through decreased caveolin-1 and endothelial nitric oxide synthase expression and localization." (PMID 30563532, 2018). "A CAV1-KO mouse model has been intensely used as a tool to study endothelial dysfunction, as well as tumor biology, owing to the increased susceptibility of these mice to cancer." (PMID 30246033, 2018). "We also asked if miR-204 is responsible for Cav1 downregulation in a pathophysiological model of endothelial dysfunction." (PMID 28181559, 2017). "We then asked if downregulation of vascular Cav1 is responsible for endothelial dysfunction due to ER stress." (PMID 28181559, 2017).
endothelial dysfunction (continued). "Accumulating evidence now suggests that in cardiovascular disease, endothelial dysfunction occurs as a result of alterations in the caveolae/Cav-1 signaling pathway." (PMID 22013533, 2012). "One particularly compelling strategy involves caveolin-derived peptides, such as Cavtratin, a Caveolin-1 scaffolding domain peptide, which has demonstrated potential in mitigating endothelial dysfunction and attenuating inflammation in cardiovascular and metabolic diseases." (PMID 40243482, 2025). "Thus, aberrant Cav-1 expression and eNOS dysfunction, particularly eNOS uncoupling, which generates superoxide (O2−) instead of NO, are proposed as key contributors to endothelial dysfunction in cardiovascular disease (CVD)." (PMID 40243482, 2025). "This function is largely attributed to Cav-1, as evidenced by studies demonstrating that Cav-1 knockout not only abolishes caveolae, but also leads to pronounced endothelial dysfunction, characterized by dysregulated nitric oxide (NO) signaling and increased vascular permeability." (PMID 40243482, 2025). "Despite previous studies’ findings on EC- Cav-1/BMPR2 depletion as an important switch towards endothelial dysfunction, more specific information about what triggers the process remains unclear." (PMID 37908354, 2023). "In addition, levels of Cav-1 were elevated and the phosphorylation of eNOS on Ser1177 was suppressed by Ang II, showed the enhanced transcytosis and endothelial dysfunction triggered by Ang II in the brain ECs." (PMID 36369944, 2022). "Furthermore, in type 1 diabetic rats, overactivation of Cav‐1 contributes to aggravated endothelial dysfunction and hypertension." (PMID 33320446, 2021). "Eight weeks of HF-diet were able to accelerate the process of endothelial dysfunction in aorta namely by increasing abundance of caveolin-1, a negative allosteric regulator of eNOS leading to endothelial dysfunction exacerbation and associated CVD25,41." (PMID 31578395, 2019). "Endothelial cells may suffer from a similar reduction in Cav-1 due to drug therapy, resulting in endothelial dysfunction." (PMID 28587148, 2017). "Moreover, MP from cultured human T cells also induced endothelial dysfunction through regulation of the protein expression for endothelial NO synthase and caveolin-1." (PMID 28468950, 2017). "In contrast to the CCl4 model, however, endothelial dysfunction caused by methionine feeding, is not due to an enhanced production of ET-1 or caveolin-1." (PMID 26539823, 2015). "Thus it can be seen that caveolae/Cav-1 participated in the protective effects of Res on endothelial dysfunction." (PMID 25419974, 2014). "In particular, the binding of caveolin-1 to eNOS is a negative regulator of eNOS activity, and the hypercholesterolemia-induced decrease of NO production is probably due to enhanced interaction of caveolin-1 with eNOS, suggesting its involvement in endothelial dysfunction." (PMID 31277498, 2019). "Since Cav-1 and caveolae are abundant and play essential roles in endothelial cell function, there has to be link with HIV induced endothelial dysfunction." (PMID 28587148, 2017). "Finally, elevated miR-204 levels in ECs contribute to endothelial dysfunction by suppressing SIRT1 expression, leading to increased endothelial endoplasmic reticulum (ER) stress, reduced Cav1 (caveolin-1) levels, and impaired vasorelaxation." (PMID 40565538, 2025). "Inhibiting Cav-1, clathrin, or EEA1 using siRNAs against these components led to the recovery of PM-localized KCa2.3 and KCa3.1 levels, suggesting that siRNAs against these components can be used to treat endothelial dysfunction." (PMID 31871552, 2019). "Given this background and the known role of Sirt1 in endothelium-dependent vascular function, we explored if lack of Sirt1 downregulates Cav1 and produces endothelial dysfunction through induction of ER stress and miR-204." (PMID 28181559, 2017).